UBA52 (ubiquitin A-52 residue ribosomal protein fusion product 1)
Description:
[Ubiquitin]: Exists either covalently attached to another protein, or free (unanchored). When covalently bound, it is conjugated to target proteins via an isopeptide bond either as a monomer (monoubiquitin), a polymer linked via different Lys residues of the ubiquitin (polyubiquitin chains) or a linear polymer linked via the initiator Met of the ubiquitin (linear polyubiquitin chains). Polyubiquitin chains, when attached to a target protein, have different functions depending on the Lys residue of the ubiquitin that is linked: Lys-6-linked may be involved in DNA repair; Lys-11-linked is involved in ERAD (endoplasmic reticulum-associated degradation) and in cell-cycle regulation; Lys-29-linked is involved in proteotoxic stress response and cell cycle; Lys-33-linked is involved in kinase modification; Lys-48-linked is involved in protein degradation via the proteasome; Lys-63-linked is involved in endocytosis, DNA-damage responses as well as in signaling processes leading to activation of the transcription factor NF-kappa-B. Linear polymer chains formed via attachment by the initiator Met lead to cell signaling. Ubiquitin is usually conjugated to Lys residues of target proteins, however, in rare cases, conjugation to Cys or Ser residues has been observed. When polyubiquitin is free (unanchored-polyubiquitin), it also has distinct roles, such as in activation of protein kinases, and in signaling. [Large ribosomal subunit protein eL40]: Component of the 60S subunit of the ribosome. Ribosomal protein L40 is essential for translation of a subset of cellular transcripts, and especially for cap-dependent translation of vesicular stomatitis virus mRNAs.
Synonyms: rpL40; CEP52; HUBCEP52; MGC57125; MGC126879; MGC126881; L40
Tractability: Small molecule: a structure with a bound ligand is known. Antibody: its Gene Ontology location is reachable by antibodies, with high confidence; the Human Protein Atlas places it where antibodies can reach. PROTAC: UniProt records ubiquitination sites on it; ubiquitination databases record sites on it; its protein half-life has been measured.
Gene: Protein-coding gene on chromosome 19 (18,571,730 to 18,577,550, forward strand). Ensembl gene ENSG00000221983.
Subcellular location: Cytoplasm (Ubiquitin); Nucleus; Cytoplasm (Large ribosomal subunit protein eL40)
Subcellular location (Human Protein Atlas): Cytosol; Acrosome; Endoplasmic reticulum; Equatorial segment; Nucleoplasm; Plasma membrane
Pathways (Reactome):
Immune System: AMPK-induced ERAD and lysosome mediated degradation of PD-L1(CD274); Activation of IRF3, IRF7 mediated by TBK1, IKKε (IKBKE); Activation of NF-kappaB in B cells; Alpha-protein kinase 1 signaling pathway; Antigen processing: Ubiquitination & Proteasome degradation; CLEC7A (Dectin-1) signaling; DDX58/IFIH1-mediated induction of interferon-alpha/beta; Dectin-1 mediated noncanonical NF-kB signaling; Downstream TCR signaling; ER-Phagosome pathway; FCERI mediated NF-kB activation; GSK3B-mediated proteasomal degradation of PD-L1(CD274); IKK complex recruitment mediated by RIP1; IRAK1 recruits IKK complex; IRAK1 recruits IKK complex upon TLR7/8 or 9 stimulation; IRAK2 mediated activation of TAK1 complex; IRAK2 mediated activation of TAK1 complex upon TLR7/8 or 9 stimulation; ISG15 antiviral mechanism; Inactivation of CSF3 (G-CSF) signaling; Interferon alpha/beta signaling; Interleukin-1 signaling; JNK (c-Jun kinases) phosphorylation and activation mediated by activated human TAK1; MAP3K8 (TPL2)-dependent MAPK1/3 activation; NIK-->noncanonical NF-kB signaling; NOD1/2 Signaling Pathway; Negative regulation of FLT3; Negative regulators of DDX58/IFIH1 signaling; PD-L1(CD274) glycosylation and translocation to plasma membrane; Regulation of NF-kappa B signaling; Regulation of TBK1, IKKε (IKBKE)-mediated activation of IRF3, IRF7; Regulation of TBK1, IKKε-mediated activation of IRF3, IRF7 upon TLR3 ligation; Regulation of innate immune responses to cytosolic DNA; Regulation of signaling by CBL; SPOP-mediated proteasomal degradation of PD-L1(CD274); Signaling by CSF1 (M-CSF) in myeloid cells; TAK1-dependent IKK and NF-kappa-B activation; TICAM1, RIP1-mediated IKK complex recruitment; TICAM1,TRAF6-dependent induction of TAK1 complex; TICAM1-dependent activation of IRF3/IRF7; TNFR2 non-canonical NF-kB pathway
and 173 more pathways
Gene Ontology:
Molecular function: protein binding; structural constituent of ribosome; protein tag activity
Biological process: cytoplasmic translation; modification-dependent protein catabolic process; negative regulation of myoblast fusion; protein modification process; protein ubiquitination; spermatogenesis; striated muscle contraction; response to insecticide; translation
Cellular component: cytoplasm; cytosolic large ribosomal subunit; cytosolic ribosome; extracellular exosome; extracellular region; lysosomal membrane; nucleus; vesicle; cytosol; endocytic vesicle membrane; endoplasmic reticulum membrane; endosome membrane; mitochondrial outer membrane; nucleoplasm; plasma membrane; ribosome
Genetic constraint (gnomAD): Loss-of-function variants: 1 observed, 16.21 expected, observed/expected ratio (o/e) 0.0617, 90% interval 0.021 to 0.29. The upper end of that interval is the gene's LOEUF score, 0.29, which puts it in group 1 of 6, group 1 being the genes least tolerant of losing a copy. Missense variants: 87 observed, 175.52 expected, observed/expected ratio (o/e) 0.5, 90% interval 0.42 to 0.59. Synonymous variants: 50 observed, 61.28 expected, observed/expected ratio (o/e) 0.82, 90% interval 0.65 to 1.03.
Homologues: Orthologues: chimpanzee KXD1 (100% identical), dog UBA52 (100% identical), guinea pig UBA52 (100% identical), macaque UBA52 (100% identical), mouse Uba52 (100% identical), pig UBA52 (100% identical), tropical clawed frog uba52 (100% identical), zebrafish uba52 (98% identical), Drosophila melanogaster RpL40 (98% identical), Caenorhabditis elegans ubq-2 (93% identical). Paralogues in human: UBC (70% identical), RPS27A (69% identical), NEDD8 (36% identical), ZFAND4 (34% identical), ANKUB1 (30% identical), UBD (26% identical), UBL4A (23% identical), ISG15 (20% identical), UBL4B (19% identical), UBB (11% identical).